EGFR (epidermal growth factor receptor)
Diseases named in the same sentence as EGFR in open-access papers (continued):
Sharing a sentence is not in itself a finding about the gene and the disease.
cancer (continued). "Among them, drug delivery vehicles using EGFR to enter the cancer cells are of specific interest, as various cytotoxic agents can be delivered this way to EGFR overexpressing cells." (PMID 36432639, 2022). "Dysregulation of EGFR is encountered in several types of cancers including head and neck, breast, lung cancers, prostrate, ovarian, glioblastomas, and other solid tumor malignancies." (PMID 35408693, 2022). "We found that EGFR (58.7%) is predominantly mutated at higher frequencies in CN_ LUAD compared to 22.1% in U.S._LUAD and other cancer types in both populations." (PMID 36163440, 2022). "Amphiregulin (AREG) is a ligand of epidermal growth factor receptor (EGFR), which is underlined to function in several aspects of cancerogenesis including cancer cell growth, invasion, metastasis, angiogenesis, and resistance to apoptosis." (PMID 36299414, 2022). "The H3K27 methylation controls the extrachromosomal amplification of EGFR, driving the drug resistance for cancer." (PMID 36246406, 2022). "The interaction between EGFR and the integrin signal pathway mobilizes cancer cells by activating matrix metalloproteinases and changing cell adhesion, ultimately causing metastasis." (PMID 35494059, 2022). "Here, we demonstrate that the metal vanadium boosts the effectiveness of OV by lowering the cancer’s natural anti-virus response by modifying the activity of EGFR, a common cellular receptor." (PMID 35572196, 2022). "It has been well documented that binding of anti-CD38 mAb Daratumumab, anti-CD20 mAb rituximab, anti-HER2 mAb trastuzumab, anti-EGFR mAb cetuximab etc. to cancer cells promotes trogocytosis mediated by monocytes and other FcγR+ cells." (PMID 35273608, 2022). "FC101 modulates the MAPK and mTOR pathways downstream of EGFR, both of which are vital to cancer cell proliferation, survival, and development of drug resistance in advanced cancer (e.g., TNBC)." (PMID 36428475, 2022). "Advances in cancer research have identified efficient tyrosine kinase inhibitors that, by interfering with EGFR function, have shown to be beneficial in EGFR-dependent cancers cases." (PMID 36080307, 2022). "NRF2 accelerates cancer cell proliferation by affecting epidermal growth factor receptor signaling and upregulating anabolism." (PMID 36300094, 2022). "Modifications to one of the epidermal growth factor receptor (EGFR) domains and cyclic peptide production, for example, were used to create a cytotoxic state for cancer cells." (PMID 35346211, 2022). "We find EGFR mutations regulate PCNA expression in NSCLC; however, there is very little evidence of how PCNA is involved in TKI failure in EGFR-mutated cancers." (PMID 36430528, 2022). "In the case of cancer, EGFR undergoes uncontrolled auto-phosphorylation that results in increased cellular proliferation and decreased apoptosis, causing cancer promotion." (PMID 35769445, 2022). "Epidermal growth factor receptor (EGFR) is a cancer biomarker, and its overexpression can signal cancer." (PMID 35457828, 2022). "Alternatively, 5-HT7R can crosstalk with EGFR by directly interacting with EGFR, as proposed for other GPCR, underlying the importance of protein–protein interaction to modulate cancer cell signaling." (PMID 35455961, 2022). "Similar to MEK1/2 inhibition, normal gastric organoids were more sensitive than cancer PDOs toward EGFR (AUCrel: 0.449 (normal) vs. 0.861 (PDOs)) and B‐RAF inhibition (AUCrel: 0.653 (normal) vs. 0.895 (PDOs))." (PMID 35993110, 2022). "By altering the localisation and distribution of EGFR in different cellular compartments, the dysregulation of endocytosis in cancer cells can therefore have a profound effect on EGFR’s regulation of the autophagic process." (PMID 35158954, 2022).
cancer (continued). "The result suggested that 3l combined with EGFR, down-regulated EGFR phosphorylation level, and regulated the proliferation of cancer cells through the EGFR-RAS-Raf-MAPK pathway." (PMID 36467103, 2022). "As a proxy of literature support we calculated the total number of publications that mention a gene in a relevant context, such as “cancer”, “resistance”, “EGFR”, “NSCLC”." (PMID 35351890, 2022). "Dysregulation of the EGFR signaling pathway is an established feature in multiple cancer types, and EGFR signaling can be regulated by classical PTPs." (PMID 36341348, 2022). "Of note, the epidermal growth factor receptor (EGFR) is a prime contributor to cancer through the involvement of four receptor tyrosine kinases (RTKs), namely, HER1, HER2, HER3,and HER4." (PMID 37654845, 2022). "According to the database of COSMIC, the world's largest and most comprehensive resource for exploring the somatic mutations in human cancer, chromosome 7 included lots of well-known cancer-related genes, including EGFR, BRAF, CDK6, MET, T1F1, and so on." (PMID 35568828, 2022). "Mesenchymal EGFR mutant cancers survived initial EGFR inhibitors because fibroblast growth factor receptor 1 (FGFR1) was expressed on the cell surface." (PMID 36313710, 2022). "The screening assay was conducted by in vitro co-cultures of U87 cancer cells and antigen-specific EGFR-CAR T cells from several healthy donors." (PMID 36085295, 2022). "Meanwhile, in the current study, it was impossible to investigate the effects of specific cancer drugs (such as regorafenib) following the administration of anti-EGFR antibody drugs." (PMID 36045384, 2022). "IR alone and IR/TMZ increased the number of GranzymeB+ CD8+ T cells, reduced the number of EGFR+ cancer cells and CD45+ cells and decreased BLI output." (PMID 35624211, 2022). "Cx, a clinically approved human IgG1 mAb, applied in a variety of epidermal growth factor receptor-overexpressing cancer types, served as model in this study." (PMID 36619384, 2022). "Recent studies revealed that morphine and oxycodone can activate EGFR and stimulate EGFR-mediated signaling pathways in cancer cells." (PMID 35999506, 2022). "The overactivation and overexpression of EGFR are related to cancer metastasis, drug resistance, poor prognosis, and lower survival rate." (PMID 35291911, 2022). "The same group, later utilized the same EC monolayer system to evaluate the extravasation rate of breast cancer cells treated with an EGFR-targeting anti-cancer drug, Cetuximab." (PMID 36439519, 2022). "Hirsutrin, hyperosid, and other key constituents present in cocoa were found to target and bind with EGFR suggesting their probable roles in inhibiting EGFR and other key protein targets in cancer biology." (PMID 35421091, 2022). "In the AURA sub-study, patients received oral anti-cancer therapy with the EGFR-TKI osimertinib after having experienced progression of their cancer during previous EGFR-TKI therapy." (PMID 34056687, 2022). "Epidermal growth factor receptor (EGFR)-family RTKs in particular have become targets for clinical intervention in human cancer." (PMID 35249128, 2022). "In our previous studies, a targeted nanomedicine for siRNA delivery was successfully developed and proved its in vitro potency for actively targeting EGFR-positive cancers." (PMID 36559172, 2022). "Cell surface HS/CS Proteoglycans (HSPGs) Syndecan-1 is known to increase cancer stemness and invasiveness through stimulating the Notch and EGFR signaling pathways and regulation of the focal adhesion kinase-Wnt signaling axis." (PMID 36612261, 2022). "To accomplish this aim, we assessed the role of EGFR and cyclin D1 according to the depth of invasion and cancer stage." (PMID 35723316, 2022). "Here, we investigated the contribution of HOTAIR in cisplatin-induced cancer cachexia and dissected the potential signaling cascade involving the epidermal growth factor receptor (EGFR), ProT, NF-κB, and HOTAIR." (PMID 36471329, 2022).
cancer (continued). "Necitumumab is anti-EGFR recombinant mAb and induces fewer allergic reactions due to the absence of murine systems and induction of antibody-dependent cell-mediated cytotoxicity (ADCC) in most cancer cells expressing EGFR." (PMID 35978836, 2022). "EGFR is expressed in normal cells in up to 100,000 molecules, yet in specific cancer types, this number is elevated and can reach 106 molecules per cell." (PMID 35806218, 2022). "In this study, we have shown that B-ASO is efficiently taken up by EGFR-FESAN in EGFR-overexpressing cancer cells and has higher anti-EGFR silencing activity than it has in case of delivery by the commercial Lipofectamine 2000 transfection agent." (PMID 36499115, 2022). "Epidermal growth factor receptor (EGFR) is one of the most potent oncogenes usually overexpressed in cancers." (PMID 35456655, 2022). "KRAS-mutated cancers are heterogeneous, and genomic commutations, MET amplification, metabolic reprogramming, and EGFR signaling represent some possible mechanisms of resistance to the KRASG12C inhibitors and immunotherapy." (PMID 36230855, 2022). "CBD was more effective in suppressing cancer cells and inducing apoptosis than the other compounds, while cells with higher EGFR expression were more likely to be affected by cannabinoid-induced cytotoxicity." (PMID 36568260, 2022). "In vivo experimental results manifested that knockdown of miR-155-5p strengthened the anticancer activity of cetuximab in an EGFR-overexpressing TNBC xenograft mouse model by prompting cancer cell pyroptosis." (PMID 36387211, 2022). "The E5 can stimulate cancer cell proliferation by forming activating complexes with growth factor receptors, such as the Epidermal Growth Factor Receptor (EGFR), resulting in a proliferative state that lasts for a long time." (PMID 35918631, 2022). "Cancer cells can increase their production of active TGF-β during the development of EGFR-TKI resistance, which triggers EMT and allow the cells to become invasive." (PMID 36304306, 2022). "In this study, binding of the TPMIL constructs to MIA PaCa‐2 cells was attenuated significantly when the cells were pre‐treated with free Cetuximab, further confirming the binding specificity of the constructs toward cancer cell EGFR." (PMID 35748165, 2022). "Nevertheless, further breakthroughs are needed to yield an appropriate standard care for patients with EGFR-mutated NSCLC, which requires gaining a deeper understanding of cancer cell dynamics in response to EGFR-TKIs." (PMID 36553449, 2022). "In NSCLC, it has been reported that anexelekto (AXL) plays a role in resistance to many anti-cancer drugs including EGFR inhibitors." (PMID 35463360, 2022). "Another way in which EVs can contribute to antibody-based cancer therapy resistance was observed using EGFR as a target." (PMID 35646668, 2022). "SPINK1 is believed to promote proliferation of cancer cells by inducing EGFR phosphorylation, which results in activation of the mitogen-activated protein kinase (MAPK) pathway." (PMID 35202241, 2022). "Numerous ATP-competitive EGFR/HER2 RTK dual inhibitory small molecules possessing various chemical structures have been reported for the treatment of cancer." (PMID 36678540, 2022). "Accumulated evidence has shown that EGFR activation increases the expression of HIF-1α in cancer cells under normoxic conditions." (PMID 36435833, 2022). "Several antigens have been targeted to treat this cancer, including epidermal growth factor receptor (EGFR), which is highly expressed in the epithelium and epithelium-derived tissues compared with normal lung tissues." (PMID 35814023, 2022).
cancer (continued). "In this regard, our previous research established the ANXA2-EGFR autocrine loop by demonstrating that ANXA2 in the cancer cell membrane plays a vital regulatory role in EGFR downstream signaling." (PMID 36224238, 2022). "Cetuximab, which was used to increase the cellular uptake of liposomes, is an anti-EGFR chimeric-murine monoclonal antibody, a biological drug that competitively binds to the EGFR on EGFR-positive cancer cells (e.g., DU145)." (PMID 35625921, 2022). "Immunohistochemical analysis revealed activation of multiple carcinogenic pathways in cancer cells, including those for angiogenesis, signal transduction by epidermal growth factor receptor, inflammation, and cell proliferation." (PMID 36605696, 2022). "Drug sensitivity analysis shows that in contrast to the association of YAP1/EGFR/MAP2K1 with drug resistance, high expressions of mTOR are favorable to cancer chemotherapy." (PMID 35655775, 2022). "Here we demonstrate that methionine deprivation in combination with EGFR inhibition can effectively inhibit the growth of H1299 cancer cells." (PMID 36361596, 2022). "All pan-cancer interactions extracted from five EGFR TKIs sensitivity specific gene networks can be found in the S1 Table." (PMID 35584089, 2022). "According to the literature, the EGFR participates in immune evasion in human cancer, for example by expediting aerobic glycolysis." (PMID 35216384, 2022). "High body weight is a novel prognostic factor for patients receiving cancer drugs with anti-EGFR antibody drugs." (PMID 36045384, 2022). "Based on these results and the recent work of our, and other, research groups, CL4 aptamer endows different polymeric nanosystems with excellent cancer cell targeting, rapid uptake and internalization capabilities in EGFR-positive TNBC cells." (PMID 35336001, 2022). "EGFR activation is a known promoter of tumorigenesis in a variety of cancers and EGFR tyrosine kinase inhibitors and blocking antibodies are mainstays of treatment." (PMID 35948530, 2022). "Taken together, these data suggest that EGFR‐targeted RBCEVs enhance the specificity of delivery to EGFR‐positive cancer cells leading to improved therapeutic efficacy of immRNA in vivo." (PMID 35430766, 2022). "Other studies have used fluorescence nanodiamond (FND) and cetuximab to target EGFR that expresses cancer cell to deliver drugs." (PMID 35203275, 2022). "All three cannabinoids had high levels of inhibition in EGFR-positive cancer cells, but low levels in normal cells." (PMID 36568260, 2022). "Epidermal Growth Factor Receptor (EGFR) signaling is dysregulated in many human cancers, including cSCC." (PMID 35408839, 2022). "Despite great therapeutic successes, the clinical use of these EGFR inhibitors inevitably leads to acquired resistance, which presents new challenges for cancer treatment." (PMID 35702041, 2022). "A previous study has demonstrated the necessity of YAP activation for evading combined EGFR/MEK inhibition in cancer cells." (PMID 36048538, 2022). "The two monoclonal antibodies were specific for CD3 on the surfaces of T cells and EGFR on the surfaces of cancer cells." (PMID 36167539, 2022). "Immunohistochemistry was used to detect the expression of EGFR in cancer tissues of patients with recurrent OSCC." (PMID 35222283, 2022). "Overall, our findings indicated that PIA NCs along with NIR can be an effective method for ablating EGFR-expressing cancer cells with minimal injury to surrounding cells." (PMID 36291827, 2022). "Several small molecule EGFR-tyrosine kinase inhibitors (TKIs) have been developed for the treatment of cancers overexpressing EGFRs including breast cancer, head and neck cancer, and non-small cell lung cancer." (PMID 36297833, 2022).
cancer (continued). "Here, we found that a STAP-2 PH domain–derived peptide inhibited STAP-2–EGFR interaction and suppressed EGFR-mediated proliferation in several cancer cell lines." (PMID 36410436, 2022). "We further described an RBCEV surface functionalization method with EGFR‐targeted nanobodies, which can enhance the delivery of RIG‐I agonists toward EGFR‐positive cancer cells, thereby improving therapeutic efficacy while reducing side effects." (PMID 35430766, 2022). "The induction of EMT by fentanyl observed in our studies is also well correlated with the previous work that EGFR cooperates signal transducer to induce EMT in cancer cells." (PMID 35999506, 2022). "EGFR plays a key role in the rapid clonal expansion of progenitor cells derived from cancer stem cells, which is particularly relevant for solid tumours." (PMID 36330452, 2022). "Epidermal growth factor receptor (EGFR) is generally upregulated in various cancer types and plays an important role in promoting cancer growth and metastasis." (PMID 35851575, 2022). "We further focused on EGFR mutations and the cancer immune response, with particular attention given to the role of EGFR activation in the cancer-immunity cycle." (PMID 35935943, 2022). "The predictive value for patient long-term prognosis and association with routinely used semantic, genetic (e.g., epidermal growth factor receptor (EGFR)), and histopathological cancer profiles were validated." (PMID 35482262, 2022). "Elevated levels of EGFR and its associated ligands (EGF and transforming growth factor (TGF)) have been found to be a common feature of a variety of cancer types." (PMID 35801486, 2022). "Another very promising strategy for cancer therapy via the EGFR downregulation is EGFR-directed gene therapy." (PMID 36499115, 2022). "In this study, we showed that 2D5 peptide acted as an inhibitor of STAP-2–EGFR interactions and suppressed EGFR-mediated cancer cell growth." (PMID 36410436, 2022). "This resulted in the attenuation of phosphorylation of EGFR and intensity of Ki-67, both which are markers of proliferation in cancer cells." (PMID 36362345, 2022). "Recently, METTL3 was shown to have a positive effect on EGFR levels in cancer cells through translational regulation." (PMID 35190939, 2022). "Particularly, inhibitors of DYRK1A are of interest for the treatment of EGFR-dependent cancer through the suppression of the cancer cells growing in EGFR-dependent tumors." (PMID 36186578, 2022). "We also enabled cancer cell-selective targeting by expressing EGF at the capsid surface to allow binding to the EGF receptor (EGFR)." (PMID 36591314, 2022). "Although it has proven difficult to accomplish in vivo, the role of the EGFR-ProT-NF-κB-HOTAIR signaling axis in cisplatin-induced cancer cachexia requires validation in animal models." (PMID 36471329, 2022). "This study involved the immunohistochemical detection of EGFR expression in cancer tissues of patients with T2DM and OSCC." (PMID 35222283, 2022). "Sahaquine, a selective HDAC6 inhibitor, reduced the level of p-glycoprotein and EGFR activity and enhanced the sensitivity of glioblastoma to anti-cancer cancer drugs such as TMZ, quercetin, and buthionine sulfoximine." (PMID 36076996, 2022). "It was previously shown that protein abundance can regulate the biological response and it is known that EGFR is overexpressed in cancer." (PMID 35748700, 2022). "Various cancer-related pathways were enriched in this panel, being “Protein processing in the ER”, “EGFR” and “Hippo signaling” pathways the most significant." (PMID 35710947, 2022). "Numerous genetic elements are involved in the pathogenesis and progression of NSCLC, including EGFR and K-Ras, which function as oncogenes and play important roles in human cancer development." (PMID 35280763, 2022).